SOX2 (SRY-box transcription factor 2)
Diseases named in the same sentence as SOX2 in open-access papers (continued):
Sharing a sentence is not in itself a finding about the gene and the disease.
cancer (continued). "To determine whether LVs were predominantly associated with nuclear SOX2− positive CSCs rather than with all cancer cells, we quantified the relative distances between LV with SOX2+ cells, as well as between LV with K5+ SOX2− cells." (PMID 37686421, 2023). "Sex determining region Y-box 2 (SOX2) is a transcription factor important in the maintenance of self-renewal, or pluripotency, of undifferentiated embryonic stem cells and SOX2 autoantibodies are being investigated -together with several others- as early detection signals for different cancers." (PMID 37767091, 2023). "Taken together, these findings provide a comprehensive understanding of the mechanism by which SOX2 and its coactivator p300 cooperatively regulate SE-mediated gene expression via transcriptional condensation, which can be a potential therapeutic target for treating cancer." (PMID 37930832, 2023). "ob-aT bASCs exhibited an increased ability to stimulate cancer stemness in highly malignant MDA-MB-231 cells by enhancing the gene expression of pluripotency and CSC associated genes such as ALDH1H1, ALDH2, c-MYC, CD34, LGR5, CXCR4, SOX2 and OCT4, fueling further their malignant potential." (PMID 36710348, 2023). "Thus, the role of SOX2 in cell cycle regulation in different cancer contexts might be highly dose-dependent." (PMID 37760529, 2023). "With regards to human cancer cell lines, that is brain, uterine cervix, lung, colon, bladder, and synovium derived cell lines, double-network hydrogel has been utilized to create spheroids with elevated levels of stemness-related genes SOX2, OCT3/4, and NANOG in vitro within 24h of seeding." (PMID 37614497, 2023). "However, although the inhibition of the canonical β-catenin signaling also improved the survival of spheroids treated with 5FU, it adversely impacted their stemness phenotype through impaired Sox2 expression and even Oct4 expression, apparently in dependence on the malignancy grade of cancer cells." (PMID 36982333, 2023). "Cancer patients within the top group (25% highest SOX2 expression; log2 counts > 10.06) have a significantly (P = 1.27 × 10−23, log-rank test) lower overall probability of survival compared with cancer patients within the bottom group (25% lowest SOX2 expression; log2 counts < 1.68)." (PMID 37738673, 2023). "KLF4, a member of the Yamanaka factor family (OCT3/4, SOX2, KLF4, and c-MYC, collectively referred to as OSKM), is known to play a crucial role in embryonic stem cells and is also implicated in maintaining stemness and EMT processes in the context of cancer stem cell models." (PMID 37762678, 2023). "Finally, we confirmed the implication of SOX2-enriched SE in MKRN1 expression of cancer stem cells." (PMID 37930832, 2023). "Therefore, we questioned whether the SRR124–134 cluster drives SOX2 expression in additional contexts other than cancer." (PMID 37738673, 2023). "Moreover, SMARCA2-negative expression was significantly associated with SOX-2-negative expression, whose presence maintains the stem cell phenotypic characteristics of cancer cells." (PMID 35289322, 2022). "The central position occupied by OCT4, SOX2, and CARM1 in the control of pluripotency in undifferentiated cells may point the way to valuable opportunities to disrupt cell phenotypes associated with the survival and proliferation of cancer stem cells." (PMID 35274101, 2022). "Another possible therapy approach, in addition to conventional cancer treatment, might target suppression of Oct4 and Sox2 transcription factors, as it is known that Oct4–Sox2 decoy ODNs can induce apoptosis, decrease proliferation, and inhibit migration, invasion, and colony formation ability." (PMID 36291969, 2022). "However, SOX2 has also been detected in the cytosol of TE and cancer cells." (PMID 36172290, 2022). "Additionally, Sox2 knockdown has been shown to result in decreased cancer stemness." (PMID 36284815, 2022).
cancer (continued). "miR-450a-5p by targeting SOX2 could regulate cancer stem cell properties and angiogenesis in CRC." (PMID 34368145, 2021). "We hypothesized that Usp9x and SOX2 axis may play a broader role in other cancers." (PMID 33613844, 2021). "Therefore, SOX2 is an attractive target for cancer therapy; however, considering that SOX2 is a transcription factor, it will be important to identify upstream or downstream regulators that could be drugged." (PMID 34809669, 2021). "Given its key role as a master regulator of cell proliferation, SOX2 represents an important scaffold for the engineering of dominant-negative synthetic DNA-binding domains (DBDs) that act by blocking or interfering with the oncogenic activity of the endogenous transcription factor in cancer cells." (PMID 34502261, 2021). "Moreover, it has been reported that AKT could interact with Sox2 or Oct4 to promote the self-renewal of cancer stem-like cells." (PMID 33637721, 2021). "In normoxia, HIF1α and SOX2 are inversely correlated, reprogramming cancer cells towards an OxPhos profile, while under hypoxic conditions, as well as in acidosis-exposed cells, the increased lactate production may promote HIF1α stabilization reducing PGC1α towards a glycolytic re-conversion." (PMID 34768751, 2021). "Moreover, it is elucidated that microenvironmental factors might play an important role in SOX2 regulation in cancer." (PMID 34768751, 2021). "Together with NANOG, SOX2, and other transcription regulators, Oct4 activated both protein-coding genes and non-coding RNAs necessary for pluripotency which correlated with cell fate determination, proliferation, metastasis, drug resistance and invaded from apoptosis in cancer cells." (PMID 34613998, 2021). "Additionally, high expression levels of both YY1 and Sox2 were common in specific types of cancer." (PMID 33728560, 2021). "Therefore, understanding how SOX2 is regulated in cancer cells is relevant to tackle tumorigenesis." (PMID 33805518, 2021). "Furthermore, the combination of these properties with enhanced tumorigenic and self-renewal capacity suggests that SOX2+ cancer cells may contribute to disease progression, potentially having negative impacts on patient prognoses." (PMID 32365581, 2020). "Furthermore, our study provides novel insights into the molecular mechanisms of cancer stemness and vasculature and may be helpful in guiding the strategies targeting miR-450a-5p-SOX2 axis for cancer treatment." (PMID 32144236, 2020). "Thus, SOX2 has been validated as an attractive anti-cancer target." (PMID 31748974, 2020). "Although high levels of SOX2 expression had been found without any genetic mutations in most of the cancers, which indicates the association of epigenetic events, certain cancers could exhibit high levels of SOX2 expression due to gene amplification." (PMID 30517668, 2020). "In some but not all of these SOX2 has been linked to cancer stemness." (PMID 31477842, 2020). "The primordial significance of SOX2 thus is the maintenance of stemness under tightly balanced conditions, while its growth stimulatory significance is context specific and becomes the predominant functional feature in dysregulated settings such as transformation and cancer." (PMID 32664542, 2020). "We observed enrichment of human embryonic stem cell pluripotency genes along with transcriptional regulation of pluripotent stem cells that might lead to activation of POU5F1 (OCT4), SOX2, CD44, NANOG, and other genes associated with self-renewal and drug resistance of cancer cells." (PMID 33339129, 2020). "The inconsistent expression phenotype of SOX2 in tumors may be due to carcinoma heterogeneity." (PMID 32144236, 2020). "Therefore, targeting SOX2 could lead to effective strategies for both cancer prevention and treatment." (PMID 30823625, 2019). "Furthermore, up-regulation of SOX2 is commonly observed in other resistant cancer cells." (PMID 30382189, 2019).
cancer (continued). "SOX2 is a stem marker found in cancer cells which could be upregulated under hypoxia." (PMID 31462898, 2019). "It is likely that miR-302 signaling pathway regulated by stem cell markers such as Nanog/Oct4/Sox2 during HA-CD44 interaction may be used as a novel therapeutic drug target to downregulate cancer stem cell (CSC) functions and to overcome chemotherapy resistance in cancer cells." (PMID 31293964, 2019). "Spheroids contain a sub-population of cancer cells exhibiting stem-like properties: increased potential for self-renewal, high ability to differentiate along the mesenchymal lineage, and enhanced expression of human embryonic stem cell pluripotency markers, such as SOX2, Nanog and OCT4." (PMID 31450858, 2019). "CD133 and SOX2 may be promising targeted molecular therapy for advanced cancer patients." (PMID 30693028, 2019). "Based on these results, agents specifically targeting SOX2 may be effective in cancer therapy." (PMID 30382189, 2019). "Hence, targeting SOX2 expression/function may potentially lead to the development of effective molecular-targeted therapies for both cancer prevention and treatment." (PMID 30823625, 2019). "The prognostic value of CD133 and SOX2 expression in advanced cancer remains unclear." (PMID 30693028, 2019). "We found that while almost all cancer cells expressed OPC-associated signal transduction factors OLIG1, OLIG2, and PDGFRA, expression of progenitor-associated transcription factors such as SOX2 and SOX10 were highly expressed in cells expressing the MAPK programme." (PMID 31427603, 2019). "Thus, the transcriptional and epigenetic landscape surrounding the Sox2 locus may look very different and requires different regulation in cancer cells versus NPs." (PMID 30038234, 2018). "Given organs, such as the intestine, glandular stomach, trachea, and taste buds express SOX2, are heavily innervated by the autonomic nervous system and are damaged by therapeutic radiation for the elimination of cancers, such a strategy may be applicable to the repair of multiple organ systems." (PMID 29335337, 2018). "Furthermore, SOX2OT knockdown is concordant with SOX2 decline in cancer cells." (PMID 30202240, 2018). "Additionally, the expression of the lung cancer associated transcription factor, NKX2-1, is highly correlated with its methylation and also clusters with several other lung- associated genes, for example, SFTA3 and SOX2, at the PTM level." (PMID 28994825, 2017). "Although miR-638 has been reported to be of inhibitory effect in the GC cell proliferation by other groups, we found it also could regulate the invasion of GC by targeting SOX2, a factor that can regulate the self-renewal of stem cells and induce stem cell-like features of cancer cells." (PMID 29296232, 2017). "Although SOX2 is associated with poor prognosis in many cancers, high SOX2 levels may not be uniformly indicative of poor patient prognosis." (PMID 28388544, 2017). "Moreover, consistent with these findings, the recurrent HCCs were enriched with the gene sets which were previously known to associate with cancer aggressiveness, including the gene sets of cell cycling, stemness (ES1, nanog, sox2, oct4, NOS, myc1, and myc2), and EMT-related genes." (PMID 28038442, 2017). "Recognizing and focusing on the role of SOX2 in drug resistance could greatly improve the treatment options for patients with a multitude of cancers, especially those with highly refractory tumors, as the ability to eradicate the TIC population is likely to be the only way to prevent recurrence." (PMID 28388544, 2017). "Additionally, 12 T cells also showed increased expression of the stemness genes Sox2, Oct4 and Nanog as well as several developmental genes known to be deregulated in cancer stem cells, such as SHH, Notch1, Gli1, and Jagged gene expression and protein expression." (PMID 26597727, 2015).
cancer (continued). "Additionally, several researchers have reported that the transcriptions of Class III β-tubulin, Sox2, and Survivin could be induced by a common factor—hypoxia inducible factor—a key intermediate factor in the evolution of cancer." (PMID 26198101, 2015). "Lastly, we underscore the role of SOX2 in the clinic and highlight new findings, which may provide novel clinical applications for SOX2 as a prognostic marker, indicator of metastasis, biomarker or potential therapeutic target in some cancer types." (PMID 25114775, 2014). "Utilizing SOX2 for cancer therapy may open a window to new therapeutic opportunities." (PMID 25114775, 2014). "SRY (sex determining region Y)-box 2, also known as SOX2, is one of the key transcriptional factors that control the unique properties of stem cells self-renewal and pluripotency and play a critical role inmaintaining the stem cell-like phenotype in cancer cells." (PMID 23990933, 2013). "Sox2 is a driver of ES self-renewal and may play a role in human cancers." (PMID 23982961, 2013). "First, to elucidate whether the PC-3 sphere cells turned into differentiated cells when sphere cells were digested into single cells for re-adherent culture (10% FBS-RPMI-1640 medium), we compared the expression levels of cancer stem cells markers, such as Oct4, Sox2 and Nanog by qRT-PCR." (PMID 23383988, 2013). "SOX2 is dysregulated in many human cancers but its role may vary in different kinds of malignancy." (PMID 20814443, 2010). "Our data adds to the current literature that also suggests higher rates of SOX2 and NANOG in metastatic DSRCT compared to primary cancer." (PMID 41614915, 2026). "Both pharmacological inhibition with Box5 and genetic ablation of RHOA effectively abrogated GNG10-induced oncogenic phenotypes and the upregulation of cancer stem cell markers (CD44, CD133, OCT4, Nanog, SOX2)." (PMID 42252561, 2026). "Although most cancer stem cell (CSC) markers were suppressed by saracatinib, expression of sex determining region Y-box-2 (Sox2) was paradoxically increased in monolayer cultures." (PMID 42065072, 2026). "PDA exposure also induced epithelial–mesenchymal transition (EMT), upregulated cancer stem cell markers (CD44, CD117, CD133, Sox2, Oct4, and Nanog), and elevated expression of metastasis- and chemoresistance-associated molecules (MMP-2, MMP-9, MDR1, and MRP1)." (PMID 41596307, 2026). "ARID1A overexpression resulted in a more differentiated ovarian cancer cell line and upon knockdown, the same cancer cell lines started expressing cancer stem cell markers: NANOG, OCT3/4, and SOX2." (PMID 40429787, 2025). "NANOG, SOX2, and OCT4 are highly critical stemness genes that promote cancer stem cell (CSCs)-related characteristics including the self-renewal of CSCs." (PMID 40806148, 2025). "In cervical cancer, acetyl-CoA, a metabolite of FAO, was shown to increase the acetylation of histone H3 on the promoters of stemness genes OCT4, SOX2, and NANOG, thereby further enhancing the cancer stemness and lymph node metastasis." (PMID 40647402, 2025). "It has been shown that activation of the IGF1R–/PI3K/AKT pathway increases the expression of cancer stemness markers NANOG and SOX2." (PMID 40243906, 2025). "SOX2, PIWI proteins, and MALAT1 were significantly elevated in cancer patients versus controls (p < 0.001), with qRT-PCR and ELISA results strongly correlated." (PMID 40674376, 2025). "These SEs regulate key pluripotency genes, such as OCT4, SOX2, and NANOG, thereby maintaining a stem-like cancer cell state." (PMID 40722714, 2025). "The TGIF2/SOX2 transcriptional axis contributes to EMT, cancer stem cell properties, and chemoresistance in PC and is a promising target for PC therapy." (PMID 39781447, 2025). "CPX induces metabolic reprogramming by activating transcription factors such as SOX2, HIF-1α, and c-Myc, thereby reprogramming non-cancer stem cells into cancer stem-like cells." (PMID 41220952, 2025).
cancer (continued). "In our study, GPT2 knockdown reduced the proportion of BCa stem cell subsets, suppressed cancer cell proliferation, and downregulated the CSC markers (ALDH1A1, SOX2, OCT4, and KMT1A)." (PMID 41323791, 2025). "In ESCA, ALDH3A1 is regulated by the core regulatory circuitry transcription factors TP63, SOX2 and KLF5 and is involved in the proliferation of cancer cells." (PMID 40529228, 2025). "While the current study focused on SOX2-dependent LUSC, this methodology is broadly applicable to other cancers, enabling the identification of previously unexplored targets across a wide range of disease contexts." (PMID 41388088, 2025). "Relative plasma expression of SOX2, PIWI proteins, and MALAT1 by qRT-PCR in cancer and control groups." (PMID 40674376, 2025). "The hypoxia-associated signaling pathways can trigger the HIF-dependent expression of molecules like KLF4, MYC, OCT4, SOX2, and NANOG, which can enhance cancer stemness and inhibit cancer cell differentiation." (PMID 39928285, 2025). "Consistently, TFAP2A enhanced the protein levels of cancer stem cell markers and stemness-related genes, including CD44, CD133, NANOG, OCT-4A and SOX2." (PMID 40727938, 2025). "Focusing here on SOX2 and KLF4, which confer stemness in cancer, we found that, in contrast to MUC1-C, EBNA1 suppresses their expression." (PMID 40764753, 2025). "Transcription factors TP63, SOX2, and KLF5 have been demonstrated to influence chromatin dynamics and contribute to cancer-specific gene ALDH3A1 inactivation in ESCC." (PMID 40523880, 2025). "In oral, pancreatic, breast, and colon cancers, miR-21 enhances cancer stem cell survival, proliferation, and invasion by targeting stemness markers, including OCT4, SOX2, CD133, and CD44, as well as signaling pathways such as Wnt and AKT/ERK1/2." (PMID 40710326, 2025). "Key differences discovered were an older age and earlier stage in patients with suppressed SOX2, who also had a higher percentage of MSI-high cancers and lower prevalence of CIN cancers." (PMID 40149431, 2025). "Chen and colleagues' work brings forth a pioneering mechanism for spurring CSC differentiation through SOX2 destabilization, thereby complementing the established use of PI3K/AKT inhibitors in cancer therapy." (PMID 40034124, 2025). "This β-catenin transfer resulted in heightened expression of active β-catenin and oncoproteins that positively regulates cancer stemness (c-Myc, OCT4, SOX2), amplifying malignant phenotypes such as radioresistance and CSC activity in recipient cells." (PMID 40657369, 2025). "Our study revealed that the knockdown of BAP31 led to a decrease in the expression of Sox2 and c-Myc, thereby establishing a connection between BAP31 and cancer stemness." (PMID 40332113, 2025). "In this study, we examined two proteins, SOX2 and NANOG, which are involved in the growth and survival of cancer stem cells." (PMID 40227667, 2025). "SOX2, PIWI proteins concentrations were significantly higher in cancer cases, confirming their elevated expression at the protein level." (PMID 40674376, 2025). "TB induced G2/M cell cycle arrest, promoted apoptosis via Bax and Caspase-3 activation, and suppressed cancer stem cell markers (NANOG, OCT4, SOX2)." (PMID 41304910, 2025). "We examined the effect of PCA as an inhibitor of the Akt/Sox2 signaling in breast CSCs from TNBC and HCC1937 cancer cells." (PMID 40076435, 2025). "SOX2 and SOX9 are frequently overexpressed in multiple cancer entities, suggesting a link between malignancy and stemness." (PMID 39180200, 2025). "In our previous investigations, we have successfully isolated and characterized CD44+ cells in which the expression of embryonic/cancer stem cell markers OCT4, SOX2, and NANOG was significantly higher than in the CD44− cell populations." (PMID 39941011, 2025).